C9orf72 (C9orf72-SMCR8 complex subunit)
Diseases named in the same sentence as C9orf72 in open-access papers (continued):
Sharing a sentence is not in itself a finding about the gene and the disease.
amyotrophic lateral sclerosis (continued). "Further, we provide deeper insights into the frequent genetic cause of amyotrophic lateral sclerosis (ALS) and frontal temporal dementia (FTD) due to the hexanucleotide repeat expansions (HRE) in the C9ORF72 gene." (PMID 37006471, 2023). "SIGNIFICANCE STATEMENT Pathogenic repeat expansion in C9orf72 is the most frequent genetic cause of FTD and amyotrophic lateral sclerosis (ALS; C9-FTD/ALS)." (PMID 36446586, 2023). "Amyotrophic lateral sclerosis (ALS) is characterised by the presence of genetic mutations in autophagy-related genes, including SQSTM1, OPTN, TBK1, VCP, and C9ORF72, which have been found to be linked to family variants of the illness." (PMID 37760929, 2023). "In amyotrophic lateral sclerosis (ALS), multiple ALS-related proteins, including TBK1, GRN, C9orf72 and TMEM106B, are implicated in endosomal sorting and endosomal lysosomal function." (PMID 38239560, 2023). "The C9orf72 repeat expansion is one of the genetic hallmarks of amyotrophic lateral sclerosis (ALS)." (PMID 37425716, 2023). "The discovery of a hexanucleotide repeat expansion in the chromosome 9 open reading frame 72 (C9orf72) gene as the most common genetic cause of FTD and amyotrophic lateral sclerosis (ALS)—often referred to as c9FTD/ALS—stoked interest in the cerebellum." (PMID 35879741, 2022). "C9orf72, fus and tardbp genes, related to Amyotrophic Lateral Sclerosis (ALS), also had reduced mRNA expression in nop56 homozygous mutants." (PMID 36009362, 2022). "The hexanucleotide expansion of the C9orf72 gene is found in 40% of familial amyotrophic lateral sclerosis (ALS) patients." (PMID 36290620, 2022). "In contrast, studies of C9orf72 in amyotrophic lateral sclerosis (ALS), a neurodegenerative disease (ND), show that alterations of G4 tracts can cause nucleolar stress, deregulate RNA alternative splicing (AS), and alter RNA binding protein localization." (PMID 35731869, 2022). "Functional studies of RAB29 in the presence of C9orf72 hexanucleotide repeat, causative of amyotrophic lateral sclerosis with FTD (ALS-FTD), have illustrated its role in vesicle trafficking." (PMID 34397087, 2021). "Mislocalization of ADAR2 was recently reported in human and mouse models of C9orf72-mediated amyotrophic lateral sclerosis (ALS)." (PMID 34535545, 2021). "In works that involved extending these studies to other diseased loci, Pribadi and colleagues attempted to remove methylation in the C9orf72 locus by gene editing in C9-related Amyotrophic lateral sclerosis and/or frontotemporal degeneration (ALS/FTD)." (PMID 33921346, 2021). "PURA has been implicated in two different nucleotide-repeat expansion disorders: fragile X-associated tremor/ataxia syndrome (FXTAS) and the disease continuum of C9orf72-mediated amyotrophic lateral sclerosis and fronto-temporal dementia (C9 ALS/FTD)." (PMID 33777106, 2021). "The presence of a hexanucleotide-repeat expansion, composed of 4 guanines and 2 cytosines (GGGGCC), within the C9orf72 locus in amyotrophic lateral sclerosis (ALS) has been shown to induce nucleolar stress and DNA damage in motor neurons." (PMID 33804735, 2021). "The most common genetic cause of amyotrophic lateral sclerosis (ALS) and fronto-temporal dementia (FTD) is a hexanucleotide repeat expansion within the C9orf72 gene." (PMID 34172817, 2021). "The most common genetic cause of familial and sporadic amyotrophic lateral sclerosis (ALS) is a GGGGCC hexanucleotide repeat expansion (HRE) in the C9orf72 gene." (PMID 33741069, 2021). "In 2011, the hexanucleotide GGGGCC (G4C2) repeat expansions of the chromosome 9 open reading frame 72 gene (C9orf72) C9orf72 gene were found as a common cause of both FTD and amyotrophic lateral sclerosis (ALS)." (PMID 32184751, 2020). "This C9orf72 NRE mutation is a hexanucleotide repeat, GGGGCCn (G4C2)n, and is currently the most prevalent genetic association for amyotrophic lateral sclerosis (ALS) and frontal temporal dementia (FTD)." (PMID 30617154, 2019).
amyotrophic lateral sclerosis (continued). "The ongoing problem of diagnostic antibody variability is highlighted well by a recent paper which tested 16 commercial antibodies (from seven different vendors) to C9ORF72, a protein specific to amyotrophic lateral sclerosis (ALS)." (PMID 31801185, 2019). "In Amyotrophic Lateral Sclerosis (ALS) and Frontotemporal Degeneration (FTD), the presence of a hexanucleotide expansion of > 30 GGGGCC repeats (termed G4C2) within the C9orf72 gene is the most prominent mutation in familial disease." (PMID 31023341, 2019). "The repeat expansion of a hexanucleotide DNA sequence (CCGGGG) found in the 5’-untranslated region of the C9orf72 gene has been shown to be causally linked to Frontotemporal Lobar Dementia and familial Amyotrophic Lateral Sclerosis (FTD/ALS)." (PMID 29912891, 2018). "Deposition of TDP-43 has been also been detected in some patients with amyotrophic lateral sclerosis (ALS), in consonance with the fact that these two diseases share some clinical and genetic features such as mutations the in TARDBP, FUS and C9orf72 genes." (PMID 27138926, 2016). "Limited copy number variations studies in amyotrophic lateral sclerosis: While CNVs in genes such as NEK1, TBK1, and C9orf72 have been linked to ALS, comprehensive, genome-wide CNV investigations are lacking." (PMID 40819305, 2026). "The C9orf72 hexanucleotide repeat expansion represents a crucial genetic link between FTD and amyotrophic lateral sclerosis (ALS), two disorders now recognized as part of a clinico-pathological spectrum." (PMID 41283303, 2025). "This study applied SFC to test the hypothesis that stepwise architecture propagating from the disease epicenter would be related with patterns of gene expression in patients with amyotrophic lateral sclerosis (ALS) carrying C9orf72 repeat expansion." (PMID 40542608, 2025). "Furthermore, ASOs have shown promising efficacy in targeting Huntington's gene (HTT) for Huntington's disease (HD), targeting SOD1 and C9ORF72 for amyotrophic lateral sclerosis (ALS), and targeting MAPT (TAU) for AD." (PMID 39226164, 2024). "A potential association between the family with the coexistence of MSA and amyotrophic lateral sclerosis (ALS) and hexanucleotide repeat expansions in C9orf72 has been documented, but pathological confirmation would be needed to differentiate phenotypical presentations." (PMID 38483626, 2024). "Pathogenic C9orf72 repeat expansions were previously identified in patients with very rare concurrence of MS and amyotrophic lateral sclerosis (ALS), but not in patients without concomitant disease." (PMID 37511014, 2023). "Telomere length comparison between 552 people with amyotrophic lateral sclerosis (ALS) with a C9orf72 repeat expansion and 907 people with ALS with normal C9orf72 repeat length using a multivariable linear regression." (PMID 36589292, 2022). "C9ORF72 contains an intronic hexanucleotide repeat (GGGGCC), whose expansion (>30 repeats) is the most common cause of familial autosomal dominant amyotrophic lateral sclerosis (ALS) and FTD with ALS." (PMID 33467748, 2021). "For example, in frontal temporal dementia (FTD) and amyotrophic lateral sclerosis (ALS), a hexamer (GGCCC) repeat in C9orf72, has accounted for both familial and sporadic forms of disease." (PMID 33800766, 2021). "Furthermore, recent discoveries show marked pleiotropy, for example, the C9orf72 expansion mutation being found in patients with clinically diagnosed FTD, amyotrophic lateral sclerosis (ALS), Huntington’s disease-like syndromes, and AD." (PMID 30279455, 2020). "Amyotrophic lateral sclerosis (ALS) patients, including C9orf72-carriers and identical twins, have highly variable disease characteristics (e.g., duration and age/site of onset), suggesting the influence of epigenetic variations." (PMID 32146547, 2020).
amyotrophic lateral sclerosis (continued). "Substantial clinical and pathological variability has been reported in patients carrying an expanded repeat in the C9orf72-SMCR8 complex subunit (C9orf72), which leads to frontotemporal dementia (FTD) and amyotrophic lateral sclerosis (ALS)." (PMID 31594549, 2019). "In 2011, an additional major genetic determinant was found in families with FTD and Amyotrophic lateral sclerosis (ALS): an intronic expansion of a hexanucleotide repeat in the C9orf72 gene, located on chromosome 9, where previous linkage studies had had identified an FTD/ALS locus." (PMID 31156380, 2019). "Several genes have been linked to the onset of amyotrophic lateral sclerosis (ALS, OMIM # 105400), including SOD1, C9ORF72, TARDBP, and FUS, though roughly 80% of cases are of unknown etiology." (PMID 29776328, 2018). "GGGGCC hexanucleotide expansions in the first intron of the C9ORF72 gene have been recently shown to be the most common genetic abnormality in FTD and amyotrophic lateral sclerosis (ALS)." (PMID 27632209, 2016). "Regions of reduced local gyrification index showed spatial convergence with cortical expression of amyotrophic lateral sclerosis-related genes such as TARDBP and C9orf72, enriched for biological processes related to protein aggregation, axon guidance and synaptic signalling." (PMID 41523190, 2026). "Additionally, it is assumed that mutations in the C9ORF72 gene may serve as a link between FTD and amyotrophic lateral sclerosis (ALS), contributing to the incidence of both conditions." (PMID 38002991, 2023). "In addition, the RNA exosome plays important roles in suppressing other unwanted RNA molecules, including expanded hexanucleotide repeat RNA in the C9orf72 gene in patients with frontotemporal lobar degeneration (FTLD) and amyotrophic lateral sclerosis (ALS)." (PMID 34948199, 2021). "Finally, familial amyotrophic lateral sclerosis (ALS) may result from mutations in the genes for TDP43, FUS, C9ORF72 and, classically, SOD1." (PMID 26035384, 2015). "Interestingly, Tau pathology has also been observed in some mixed amyotrophic lateral sclerosis (ALS)/FTD cases bearing GGGGCC expansions in C9ORF72, suggesting that some patients with nucleotide repeat expansions could develop a mixed pathology." (PMID 24409116, 2014). "Here, we provide insight into gene regulation at the C9orf72 locus that will directly impact the development of therapeutics for C9orf72-related diseases including frontotemporal dementia (FTD) and ALS (amyotrophic lateral sclerosis)." (PMID 38621131, 2024). "Age at onset of amyotrophic lateral sclerosis (ALS) is highly variable (eg, 27–74 years in carriers of the G4C2-expansion in C9orf72)." (PMID 33892821, 2021). "To pilot the concept that excellent antibodies can be found among those that are commercially available if one carries out a systematic analysis, we studied the major amyotrophic lateral sclerosis (ALS, OMIM #105400) disease gene product, C9ORF72." (PMID 31612854, 2019). "In most cases of amyotrophic lateral sclerosis, there is no family history associated, but in about 10% of cases, a dominantly inherited autosomal mutation occurs in distinct genes, such as in superoxide dismutase 1 (SOD1), C9orf72, and TAR DNA-binding protein 43 (TDP-43) genes." (PMID 37259454, 2023). "For instance, the MAPT pathway is involved in the aetiopathogenesis of Alzheimer’s disease (AD), Parkinson’s disease (PD), parkinsonism, and amyotrophic lateral sclerosis (ALS); GRN in AD, PD, parkinsonism, motor neuron disease (MND); and C9orf72 in ALS, AD, and parkinsonism." (PMID 31405128, 2019). "Amyotrophic lateral sclerosis (ALS), which appears to spread through the neuroaxis in a spatiotemporally restricted manner, is linked to heritable mutations in genes encoding SOD1, TDP-43, FUS, C9ORF72, or can occur sporadically without recognized genetic mutations." (PMID 26926802, 2016).
amyotrophic lateral sclerosis (continued). "Amyotrophic lateral sclerosis (ALS) and frontotemporal dementia share genetic disruptions (for example, C9orf72, OPTN, VCP, TMEM106B and progranulin (PGRN)) that impair normal Golgi–endolysosomal trafficking, severely reducing intracellular protein handling and degradation capabilities." (PMID 41254240, 2025).
dementia (57 papers, 2013 to 2026). Loss of intellectual abilities interfering with an individual's social and occupational functions. "A similar pattern of greater cognitive decline in females than males was observed in female C9orf72 variant carriers with dementia; functional decline was similar across females and males with dementia." (PMID 40277077, 2025). "Age-specific cumulative incidence of ALS and dementia was estimated using Kaplan–Meier and competing risk models in C9orf72 HRE carriers compared to matched controls in UK Biobank." (PMID 40682810, 2025). "Previous reports point out that cognitive decline in ALS is associated with old age, low education level, severity of the disease measured with the ALS-FRS-r scale, C9orf72 gene mutation, and family history of dementia." (PMID 38105306, 2024). "FTD is also more likely to be inherited than other dementia types, with autosomal‐dominant inheritance occurring in 20–50% of cases (usually the C9orf72 mutation)." (PMID 36807325, 2023). "PPI network that demonstrated proteins such as PSEN1, PSEN2, APP, MAPT, and C9orf72 had abundant interactions with other proteins, which was consistent with the important roles of these dementia pathogenic genes." (PMID 34720994, 2021). "Compared with these 2 genetic groups, C9orf72+ was associated with attenuated increases in the rate of volume loss, even with transition to dementia." (PMID 33112398, 2020). "The objective of this study was to determine the frequency of C9orf72 repeat expansions in a Bulgarian dementia cohort and to delineate the associated clinical features." (PMID 30550541, 2018). "In summary, a complete screening for mutations in MAPT, GRN and C9ORF72 genes revealed a frequency of 5.4% of pathogenic mutations in a random cohort of 93 Turkish index patients with dementia." (PMID 27632209, 2016). "Of the total dementia incidence linked to C9orf72, 41% was accrued between ages 75–80." (PMID 40682810, 2025). "In prodromal FTD and presymptomatic mutation carriers (GRN, MAPT, C9orf72), elevated NfL may herald pheno-conversion to full-blown dementia." (PMID 39519389, 2024). "As C9orf72 repeat expansions are associated with dementia, cases with AD were screened to determine whether the GGGGCC repeat also contributed to AD." (PMID 25731823, 2015). "Therefore we investigated whether MAPT, GRN and C9ORF72 gene mutations are major contributors to dementia in a random, unselected Turkish cohort of dementia patients." (PMID 27632209, 2016). "The connection between this pathway and major risk factors for dementia such as APOE, TREM2, c9orf72 highlights cGAS-STING pathway as a common convergence point in neuro-immune axis, affecting disease onset and progression." (PMID 41300248, 2025). "Cumulative incidence of ALS and dementia in individuals carrying more than 30 repeats in C9orf72 was 58% (50%–65%) at age 80 compared to 5.8% (4.6%–7.0%) in controls (Plog-rank < 0.001), assuming survival to this age." (PMID 40682810, 2025). "In cases of prodromal FTD and presymptomatic mutation carriers (GRN, MAPT, C9orf72, TARDBP), elevated NfL concentrations appear to be a harbinger of pheno-conversion to full-blown dementia." (PMID 39519389, 2024). "For C9orf72 patients in particular, the double threat of either developing dementia or ALS is particularly difficult and having the opportunity to explore their situation with genetic counsellors can be therapeutic." (PMID 37548032, 2024). "We analyzed baseline visit data of known carriers of a pathogenic variant in the c9orf72, GRN, or MAPT gene from the Genetic Frontotemporal Dementia Initiative cohort study." (PMID 35948443, 2022). "Specifically, GRN carriers had a tendency of a faster increase of mean and radial diffusivity values and C9orf72 carriers had a tendency of a faster decline of fractional anisotropy values as they reached closer to the expected age of dementia onset." (PMID 36632182, 2022).